HCAR3 (hydroxycarboxylic acid receptor 3)
Description:
G protein-coupled receptor for 3-hydroxyoctanoate, a fatty acid beta-oxidation intermediate. Signals through the inhibitory G(i)/o family of G proteins. Acts as a negative feedback regulator of adipocyte lipolysis, helping to counterbalance prolipolytic signals during physiological or pathological elevations in beta-oxidation. Acts as a low affinity receptor for nicotinic acid. This pharmacological effect requires nicotinic acid doses that are much higher than those provided by a normal diet.
Synonyms: GPR109B; HCA3; HM74; PUMAG; Puma-g
Tractability: Small molecule: a structure with a bound ligand is known; it belongs to a druggable protein family. Antibody: its Gene Ontology location is reachable by antibodies, with high confidence; UniProt places it where antibodies can reach, with medium confidence; UniProt predicts a signal peptide or a membrane-spanning region. PROTAC: a small molecule that binds it is known.
Target class: Family A G protein-coupled receptor; Small molecule receptor (family A GPCR); Carboxylic acid receptor; Hydroxycarboxylic acid receptor; Membrane receptor
Gene: Protein-coding gene on chromosome 12 (122,714,756 to 122,716,811, reverse strand). Ensembl gene ENSG00000255398.
Subcellular location: Cell membrane
Subcellular location (Human Protein Atlas): Cell Junctions
Pathways (Reactome):
Signal Transduction: G alpha (i) signalling events; Hydroxycarboxylic acid-binding receptors
Gene Ontology:
Molecular function: G protein-coupled receptor activity; protein binding; nicotinic acid receptor activity
Biological process: adenylate cyclase-inhibiting G protein-coupled receptor signaling pathway; negative regulation of lipid catabolic process; G protein-coupled receptor signaling pathway
Cellular component: plasma membrane; membrane
Genetic constraint (gnomAD): Loss-of-function variants: 0 observed, 0.56 expected, observed/expected ratio (o/e) 0, 90% interval 0 to 1.82. That is too few expected variants to judge how well the gene tolerates losing a copy. Missense variants: 404 observed, 481.63 expected, observed/expected ratio (o/e) 0.84, 90% interval 0.77 to 0.91. Synonymous variants: 167 observed, 186.19 expected, observed/expected ratio (o/e) 0.9, 90% interval 0.79 to 1.02.
Homologues: Orthologues: chimpanzee HCAR3 (82% identical), dog HCAR2 (79% identical), rat Hcar2 (74% identical), mouse Hcar2 (73% identical), guinea pig Hcar2 (70% identical). Paralogues in human: HCAR2 (89% identical), HCAR1 (46% identical), OXER1 (30% identical), GPR31 (27% identical), P2RY1 (23% identical), P2RY4 (22% identical), P2RY2 (21% identical), FFAR3 (19% identical), GPR42 (19% identical), P2RY6 (19% identical), OXGR1 (18% identical), SUCNR1 (18% identical), and 3 more.
Diseases named in the same sentence as HCAR3 in open-access papers:
HCAR3 is named in the same sentence as 37 diseases in open-access papers, as found by Europe PMC text mining. Sharing a sentence is not in itself a finding about the gene and the disease. The quoted sentences say what the papers report.
breast cancer (9 papers, 2010 to 2025). A primary or metastatic malignant neoplasm involving the breast. "In addition to metabolism regulation, the expression level of HCAR3 is closely associated with colorectal cancer and breast cancer, hence, HCAR3 is recognized as a potential therapeutic target for these two types of cancer." (PMID 41359625, 2025). "Thus, we sought to identify germline variants in HCAR1, HCAR2, and HCAR3 that could potentially be associated with breast cancer risk." (PMID 34852802, 2021). "HCAR3 expression in primary breast cancer cells was approximately 50-fold higher in comparison to the MCF12A epithelial breast cell line." (PMID 40650047, 2025). "HCAR3 activates Gi signaling in immune cells and is also a therapeutic target for breast cancer and inflammatory bowel diseases, and these diseases cause hypoxia response." (PMID 35885976, 2022). "Though better known for regulating lipid metabolism in adipocytes, more recently, HCARs have been functionally associated with breast cancer proliferation/survival; HCAR2 has been described as a tumor suppressor and HCAR1 and HCAR3 as oncogenes." (PMID 34852802, 2021). "HCAR3 expression has, however, been shown to be induced in breast cancer patient samples, where it plays a role in controlling intracellular lipid/FA metabolism." (PMID 28993767, 2017). "Previous studies revealed that HCAR3 in breast cancer is involved in lipid metabolism." (PMID 40650047, 2025). "Moreover, HCAR3 is essential for the metabolism and proliferation of breast cancer cells." (PMID 34722771, 2021). "In contrast, CXCL9 has been shown to predict good outcomes for cancer patients; HCAR3 and GNG4 exhibit suppressor effects on the process of tumorigenesis in mammary cancer and in GBM." (PMID 31469863, 2019). "Importantly, siRNA-mediated downregulation of HCAR3 led to reduced viability and the relative ATP levels in BT-474 and HCC1954 breast cancer cells, whereas HCAR3 overexpression increased viability in these cell lines." (PMID 40650047, 2025). "Moreover, HCAR3 silencing triggered cell death in BT-474, HCC1954, and HCC38 breast cancer cells." (PMID 40650047, 2025).
colorectal cancer (5 papers, 2019 to 2025). A primary or metastatic malignant neoplasm that affects the colon or rectum. "Integrated bioinformatic and experimental analyses have identified HCAR3 as a potential biomarker implicated in the pathogenesis of colorectal cancer." (PMID 40650047, 2025). "In CMS4, ten genes from the HCAR3 module are associated with the prediction of patient survival, and the HCAR3 gene is especially important, as it is engaged in multiple interactions and thus might be worthy of further attention with respect to the development of drugs against colorectal cancer." (PMID 31469863, 2019). "Notably, HCAR3 expression has been correlated with clinical outcomes, such as overall survival, in patients diagnosed with colorectal cancer and cervical cancer." (PMID 40650047, 2025). "A single study identified HCAR3 as a potential target in colorectal cancer." (PMID 34948292, 2021). "The function of HCAR3 in CRC remains to be elucidated; however, a member of the same HCA receptor family with similar structure, named, HCAR2, which functions as a tumor suppressor gene, has been reported to have reduced expression levels in colorectal cancer cell lines." (PMID 31469863, 2019).
coronary artery disease (2 papers, 2021 to 2023). "For example, HCAR3 is one of the DEGs involved in coronary artery disease." (PMID 36983834, 2023). "It was also indicated that HCAR3 could be involved in sepsis and coronary heart disease." (PMID 34948292, 2021).
dyslipidemia (2 papers, 2025). "Owing to its pivotal role in lipid metabolism, we conducted a virtual screening study targeting HCAR3 to identify potential drug candidates for dyslipidemia." (PMID 41011161, 2025). "The hydroxycarboxylic acid receptors (HCAR2 and HCAR3), also known as prototypical metabolite-sensing receptors, are key targets for treating dyslipidemia and metabolic disorders." (PMID 41359625, 2025). "Compared to HCAR2, activation of HCAR3 can effectively control lipid levels while avoiding the side effect of flushing, making it a more promising therapeutic target for dyslipidemia treatment." (PMID 41359625, 2025). "Given its pivotal role in lipid metabolism, HCAR3 presents a promising therapeutic target for managing dyslipidemia and other metabolic disorders, including diabetes mellitus and obesity." (PMID 41011161, 2025). "This makes HCAR3 a compelling target for developing drugs against dyslipidemia." (PMID 41011161, 2025). "HCAR2 shares the highest sequence similarity with HCAR3 in HCAR family, and is considered to be a molecular target for regulating dyslipidemia, activated by the endogenous ligand 3-hydroxybutyric acid." (PMID 41359625, 2025). "Acifran is a clinically-used drug that primarily targets both HCAR2 (EC50 = 10−5.7M) and HCAR3 (EC50 = 10−4.7M), to treat hypertriglyceridemia, type 2 diabetes, and metabolic syndrome." (PMID 41359625, 2025).
melanoma (2 papers, 2020 to 2025). A malignant, usually aggressive tumor composed of atypical, neoplastic melanocytes. "Although the mutations and oncogenic potential of HCAR3 in some types of cancer might be disturbing, individuals with melanoma exhibit markedly lower levels of HCAR3 gene expression relative to healthy skin samples, according to GEPIA2 database results." (PMID 40650047, 2025). "GEPIA2 analysis indicated a strong reduction of HCAR2 and HCAR3 expression in melanoma patients as compared to normal skin controls." (PMID 33028392, 2020). "Finally, we show for the first time that the expression levels of Niacin receptors HCAR2 and HCAR3 is almost abolished in human melanoma samples." (PMID 33028392, 2020). "Interestingly, HCAR3 expression was lower in metastatic melanoma than in primary melanoma samples." (PMID 40650047, 2025).
Sepsis (2 papers, 2021). Sepsis is defined as life-threatening organ dysfunction caused by a dysregulated host response to infection. "Artificial intelligence systems identified eight out of twenty novel genetic markers (SDC4, CLEC5A, TCN1, MS4A3, HCAR3, OLAH, PLCB1, and NLRP1) that help predict sepsis severity or mortality." (PMID 33692779, 2021).
cervical cancer (1 paper, 2021). A primary or metastatic malignant neoplasm involving the cervix. "Previous studies reported that higher expression of HCAR3 was negatively correlated with survival time of cervical cancer patients." (PMID 34419055, 2021).
cervical squamous cell carcinoma (1 paper, 2025). A squamous cell carcinoma arising from the cervical epithelium. "Additionally, survival analysis revealed that HCAR3 was negatively associated with the survival rate of patients diagnosed with cervical squamous cell carcinoma and endocervical adenocarcinoma." (PMID 40650047, 2025).
colon adenocarcinoma (1 paper, 2025). "Importantly, GEPIA2-based transcriptomic analysis revealed the correlations between the expression of HCAR3 and MSH6, NOD2, and SMAD4 in colon adenocarcinoma, but not in control tissue." (PMID 40650047, 2025).
esophageal squamous cell carcinoma (1 paper, 2025). Esophageal squamous cell carcinoma (ESCC) is a type of esophageal carcinoma (EC) that can affect any part of the esophagus, but is usually located in the upper or middle third. "HCAR3 has been identified as one of the genes used to construct an immune-related gene prognostic index (IRGPI) for esophageal squamous cell carcinoma (ESCC)." (PMID 40650047, 2025).
leprosy (1 paper, 2020). Leprosy is a chronic infectious disease affecting primarily the skin and peripheral nervous system. "When we directly compared LCs between a single leprosy biopsy and a single normal skin biopsy from which we performed bead-based LC enrichment (STAR Methods), we detected elevated expression of IDO1, STAT1, HCAR3, and MHC class I molecules (HLA-A, HLA-B, and HLA-F) in LCs in leprosy infection." (PMID 33053333, 2020).
pancreatic cancer (1 paper, 2020). "The prognosis significance, biological functions and molecular mechanisms of the factors, including HCAR3, PPY, RFWD2, WSPAR and Amcinonide, should be investigated alone and in combination to facilitate the translational research of pancreatic cancer." (PMID 32724299, 2020). "While the remaining two genes, HCAR3 (Hydroxy-Carboxylic Acid Receptor 3) and PPY (Pancreatic Polypeptide), have not previously been linked with pancreatic cancer prognosis yet, this study provides a theoretical basis for investigating their potential role in pancreatic cancer." (PMID 32724299, 2020).
tumor (7 papers, 2019 to 2025). "The AhR- and HCAR3-dependent pathways have been implicated in the microbiota-mediated immunomodulation of the tumor microenvironment in gastric cancer." (PMID 40650047, 2025). "These variants were exclusively identified in HCAR1 and HCAR3, which is notable considering their suggested oncogenic role and requirement for BC proliferation/survival compared to the demonstrated tumor suppressor properties of HCAR2." (PMID 34852802, 2021). "Emerging evidence implicates HCAR3 in key oncogenic processes, including cell proliferation, motility, and metabolic reprogramming of tumor cells." (PMID 40650047, 2025). "Particular attention is given to the potential functional interplay between KYNA and HCAR3, including receptor-mediated signaling pathways and their downstream biological effects in tumor cells." (PMID 40650047, 2025). "HCAR3 and INSL5 were expressed in tumor tissue and these were associated with poor survival and warrant further study with regard to their potential utility as CRC therapeutic targets." (PMID 34419055, 2021). "HCAR3 and INSL5 were expressed in tumor tissue and these were associated with poor survival and warrant further studies as potential therapeutic targets." (PMID 34419055, 2021). "The observed heterogeneity in HCAR3 expression across tumor types suggests that its functional activity and downstream biological effects may be context-dependent and vary among distinct cancer subtypes." (PMID 40650047, 2025). "The hypothesis that KYNA may serve as a functional ligand for HCAR3, affecting cancer cell biology and modulating the immune response in the tumor microenvironment, represents a novel, interesting research direction." (PMID 40650047, 2025). "We noted an increased tumor mutation burden and a higher frequency of specific known driver mutations when compared to The Cancer Genome Atlas database; we also found novel mutations in MUC3A, MUC5AC, HCAR3, ORT2B, and PABPC." (PMID 36382570, 2023). "Moreover, it presents a comprehensive analysis of the potential functional and molecular interactions between kynurenic acid and HCAR3 in the context of cancer pathophysiology, which may have significant implications for tumor immunomodulation and the development of new therapeutic strategies." (PMID 40650047, 2025). "The median relative expression of HCAR3 was 1.87 in paracancerous tissues and 3.04 in ESCC tissues, which was increased in tumor tissues (Wilcox test, P = 0.18)." (PMID 34722771, 2021). "IHC assays were also performed for these samples, which were consistent with western blot results, and there was no significant HCAR3 protein signal increase compared to the adjacent non-tumor tissues." (PMID 34419055, 2021). "Furthermore, the differential expression of HCAR3 and INLS5 was validated in clinical tumor samples by Real-time quantitative PCR analysis, western blotting analysis, and immunohistochemistry analysis." (PMID 34419055, 2021).
cancer (6 papers, 2019 to 2025). A tumor composed of atypical neoplastic, often pleomorphic cells that invade other tissues. "Given the growing recognition of metabolic reprogramming as a hallmark of cancer, this review explores a potential interaction network between HCAR3 and its putative endogenous ligand, KYNA." (PMID 40650047, 2025). "Notably, HCAR3 is considered a metabolite sensor, and metabolic dysregulation, including tryptophan metabolism, is a hallmark of cancer pathophysiology." (PMID 40650047, 2025). "Accordingly, the following sections will explore the potential roles of HCAR3 in specific cancer entities." (PMID 40650047, 2025). "This review focuses on the potential role of HCAR3 in cancer initiation, progression, and metastasis." (PMID 40650047, 2025). "The expression profile of HCAR3 changes significantly in the context of cancer, particularly in skin squamous cell carcinoma (SCC)." (PMID 40650047, 2025). "Recent studies identified a functional interplay between HCAR3 and AhR in cancer." (PMID 40650047, 2025). "Moreover, dysregulation of the kynurenine pathway and altered HCAR3 expression have been reported across various malignancies, reinforcing the plausibility of their functional interplay in cancer pathophysiology." (PMID 40650047, 2025). "Further studies indicate HCAR3’s role in regulating cellular processes relevant to cancer biology." (PMID 40650047, 2025). "Accordingly, this review aims to elucidate the potential role of HCAR3 in cancer initiation, progression, and metastasis, and to evaluate whether current evidence confirms its involvement in oncogenesis." (PMID 40650047, 2025). "Moreover, the review also provides a comprehensive analysis of the potential crosstalk between HCAR3 and the kynurenine metabolic axis within the context of cancer pathophysiology." (PMID 40650047, 2025). "Additionally, modulation of HCAR3 activity and/or the kynurenine pathway may represent a new therapeutic strategy in cancer treatment." (PMID 40650047, 2025). "Previous studies suggest that HCAR3 may play an important role in the cancer pathophysiology." (PMID 40650047, 2025). "Elucidating the potential HCAR3–KYNA axis in cancer may have significant clinical and therapeutic implications, as HCAR3 may represent a new prognostic and predictive biomarker in various cancer types, potentially facilitating personalized treatment strategies." (PMID 40650047, 2025). "Additionally, KYNA may directly influence cancer cell biology via activation of specific receptors, including potentially HCAR3, leading to activation of signaling pathways involved in cell survival and proliferation." (PMID 40650047, 2025). "Due to the limited number of published studies, it is currently not possible to definitively determine whether the interaction between HCAR3 and KYNA plays a role in cancer initiation, progression, or metastasis." (PMID 40650047, 2025).
metabolic disorders (2 papers, 2025). "The hydroxycarboxylic acid receptors HCAR2 and HCAR3 are key targets for treating metabolic disorders, but the structural and ligand-binding properties of HCAR3 remain less understood." (PMID 41359625, 2025).
cardiovascular disease (1 paper, 2021). "Overall, 86 genes were identified to significantly modify the cardiovascular disease severity in PXE, of which four genes are present in both tests (HCAR3, CNGB3, SI, and PRKAR1A)." (PMID 34169069, 2021).
immune disease (1 paper, 2022). "We have demonstrated that KYNU and the requirement for tryptophan via WARS, association of the transcriptional activators AHR and HCAR3, along with ADPR and PARP1, are sufficient drivers for persistent immune disease." (PMID 36499104, 2022).
infection (1 paper, 2017). The state of being infected such as from the introduction of a foreign agent such as serum, vaccine, antigenic substance or organism. "As infection progressed in the adult-derived DCs, similar expression changes as those observed in cord DCs were observed for all GPCR genes, but GNG11 and HCAR3 that did not exhibit an altered gene expression." (PMID 28993767, 2017).
HCAR3 also shares sentences with these, for which no sentence is quoted: inflammatory bowel disease (2 papers); acute respiratory distress syndrome (1); aneuploidy (1); bladder urothelial carcinoma (1); endocervical adenocarcinoma (1); head and neck squamous cell carcinoma (1); hematologic malignancies (1); Hypertension (1); IgA nephropathy (1); intestinal neoplasm (1); kidney (1); lung squamous cell carcinoma (1); lupus nephritis (1); lymphoma (1); malaria (1); Obesity (1); sarcoma (1); squamous cell carcinoma (1); viral infection (1).